INS (insulin)
Diseases named in the same sentence as INS in open-access papers (continued):
Sharing a sentence is not in itself a finding about the gene and the disease.
malnutrition (154 papers, 2008 to 2026). Inadequate nutrition resulting from poor diet, malabsorption, or abnormal nutrient distribution. "Studies have shown that the underlying cause of malnutrition in DM patients is impaired insulin secretion." (PMID 38611651, 2024). "Hypoinsulinemic hypoglycemia can result from excess alcohol consumption, malnutrition or starvation, and deficiency of insulin-antagonistic counter-regulatory hormones." (PMID 38957156, 2024). "Among the 12 who used insulin and who underwent hypoglycaemic episodes, 2 (17%) were at risk of malnutrition." (PMID 37817166, 2023). "For example, in the AM phenotype, due to the significant weight loss and malnutrition, early use of insulin should be considered due to its potentially useful weight gain and anabolic properties." (PMID 37367862, 2023). "Along with the infection risk, insulin is a potent anabolic hormone, with deficiency promoting catabolism and malnutrition and impairing lung function via reduced respiratory muscle mass." (PMID 35431976, 2022). "Increasing severity of prior malnutrition, as indicated by BMI, was associated with lower plasma insulin at all time points in univariable analysis." (PMID 33740034, 2021). "In unadjusted analyses, increasing severity of prior malnutrition was associated with lower insulin concentration." (PMID 33740034, 2021). "Early postnatal malnutrition was associated with decreased insulin sensitivity and glucose intolerance in young Mexican men, independent of birth weight." (PMID 33201860, 2020). "Wagner grades 3–5, with CVD and using insulin may increase the risk of malnutrition in diabetic patients." (PMID 39364802, 2024). "Although adiponectin has anti-inflammatory, anti-atherosclerosis, and insulin sensitization effects, adiponectin can also increase the energy consumption of patients, thereby accelerating body’s catabolism and causing malnutrition." (PMID 37038353, 2023). "Also, most participants in the insulin-deficient subgroup (first approach) were relocated to the malnutrition-related subgroup (second approach)." (PMID 37402743, 2023). "Malnutrition is accompanied by loss of muscle mass and muscle function and exaggerates the observed loss of fat-free mass in elderly persons, reducing metabolic reserve and insulin sensitivity." (PMID 35193560, 2022). "In this secondary analysis, we used data from the cohort to investigate whether prior adult malnutrition was associated with insulin production." (PMID 33740034, 2021). "Delayed gastric emptying may cause disturbances in postprandial glucose, insulin, and ghrelin levels and further results in low energy intake, contributing to malnutrition and increased morbidity." (PMID 34540991, 2021). "Therefore, it is possible that the increased insulin sensitivity was caused by a response to nutritional deficiency similar to MCD." (PMID 34390210, 2021). "Malnutrition increased the risk of diverse forms of ill health, by imposing interconnected biological pathways, involving imbalance of the gut microbiome, inflammation, metabolic dysregulation, and impaired insulin signaling." (PMID 32937736, 2020). "Several transplant-specific factors predispose KTR for development of malnutrition, including infectious complications, rejection episodes, insulin resistance, use of immunosuppressive medication and the immune response to the graft, which function as catabolic stimuli." (PMID 32824065, 2020). "Therefore, severe pancreatic lesions would inevitably cause a reduction in insulin secretion, skeletal muscle malnutrition, protein synthesis inhibition, and increase protein decomposition." (PMID 27911874, 2016). "Malnutrition or starvation is known to repress mTor activation (most likely via Insulin/IGF deficiency) and may contribute to impaired wound healing in some BU patients." (PMID 24762629, 2014). "A possible explanation could be that protein-calorie malnutrition and magnesium deficiency may cause low insulin secretion and a low pancreatic insuline store." (PMID 25072784, 2014).
malnutrition (continued). "Furthermore, malnutrition, particularly protein and calorie deficiencies, reduces the availability of essential amino acids and glucose, both of which are critical signals for insulin release." (PMID 40735237, 2025). "Additionally, weight-loss surgery may lead to postoperative malnutrition, gastric emptying disorders, abnormal insulin secretion, among other issues." (PMID 38962677, 2024). "Malnutrition has a well-known and clinically relevant enhancing effect on insulin sensitivity, but the findings of GWASs indicate that patients with AN may be especially susceptible to developing increased insulin sensitivity." (PMID 35893544, 2022). "The less energy expenditure could be due to a consequence of a lower increase in lean body mass, or other mechanisms, such as, decreased IGF-1 levels and a higher ratio of cortisol to insulin associated with malnutrition, acting in favour of conservation of energy and/or body fat." (PMID 29965973, 2018). "Glucose metabolism in CKD patients is affected by increased insulin resistance, impaired counter-regulatory hormone response (cortisol, growth hormone), malnutrition, and variability in exposure to oral hypoglycemic agents and exogenous insulin." (PMID 40764800, 2025). "Patients with multiple chronic diseases often experience altered drug metabolism, polypharmacy, and malnutrition, potentially interfering with glucose regulation and insulin sensitivity." (PMID 41040859, 2025). "Several explanations exist for age being a risk factor for MetS, including a decline in the ability of pancreatic beta cells to produce insulin, oxidative stress, comorbidities, malnutrition, and physical inactivity." (PMID 39765954, 2024). "In diabetics, a higher preoperative glycemia, a higher preoperative glycated hemoglobin (HbA1c) and the need of insulin therapy were related to malnutrition." (PMID 38805173, 2024). "In this condition, several dysfunctions arise as a consequence of fetal adaptation to malnutrition, particularly the development of insulin resistance (IR) and the reduction of insulin production." (PMID 39599588, 2024). "In addition to its anti-oxidant and anti-inflammatory properties, Se supplementation to improve malnutrition in patients may also be associated with its effects on fat digestion and absorption, nutrient utilization, reduction of ketone bodies, and improved insulin action." (PMID 37038353, 2023). "In cancer, malnutrition is a result of a combination of anorexia, gastrointestinal symptoms and metabolic dysregulation, including insulin resistance." (PMID 37375630, 2023). "The malnutrition-related subgroup had the lowest serum insulin concentration and HOMA-beta, and showed the lowest BMI, waist circumference and fat mass." (PMID 37402743, 2023). "Inflammation has been identified as a key driver for disease-related malnutrition, leading to anorexia, reduced food intake, muscle catabolism, and insulin resistance, which are stimulating a catabolic state." (PMID 36904164, 2023). "Existing studies have shown that malnutrition and microinflammatory state, insulin resistance, FGF23/klotho axis abnormalities, and other factors are interconnected and ultimately jointly promote the occurrence of vascular calcification." (PMID 34367315, 2021). "It is well established that HD patients suffer from malnutrition due to metabolic and hormonal derangements, insulin deprivation, inflammation, inadequate nutrient intake, and adverse effects of renal replacement therapy." (PMID 33920330, 2021). "We collected clinical and biochemical data, evaluated insulin resistance, body composition, malnutrition [by Malnutrition Inflammation Score (MIS)] and tested muscle function (by hand-grip strength, six-minute walking test and a questionnaire on fatigue)." (PMID 31829144, 2019). "This suggests that vagotomy-induced reduction in insulin clearance is a phenomenon observed only in an obese mouse model, probably because they experienced malnutrition during early life." (PMID 28951790, 2017).
malnutrition (continued). "In advanced pancreatogenic diabetes, insulin therapy is the preferred treatment, and especially during acute episodes of pancreatitis or hospitalized patients, and severe malnutrition patients in which the anabolic effects of insulin are desired." (PMID 28101143, 2017). "Because insulin plays a key role in the genesis of metabolic disease, this review will be dedicated to the effects of malnutrition during lactation on the regulation of insulin secretion via putative modifications of the autonomic nervous system (ANS)." (PMID 22967456, 2012). "Studies of dietary transition from rural malnutrition to different diets in urban settings, the role of maternal malnutrition, extent and mechanisms of insulin-resistance, and barriers and resilience of communities for prevention." (PMID 20482860, 2010). "Tumor growth may result in significant nutrient depletion and malnutrition-related symptoms, primarily due to systemic inflammatory response induced by the tumor growth, leading to insulin resistance and accelerated catabolism of proteins and adipose tissues." (PMID 39874306, 2025). "Inflammation and nutrition exhibit an interdependent relationship, where inflammation may trigger insulin resistance and catabolism, thus exacerbating malnutrition." (PMID 41031357, 2025). "Inflammation is an element involved in several pathologies and has been recognized as a pivotal factor contributing to disease-related malnutrition, inducing anorexia, decreased food intake, muscle catabolism, and insulin resistance, ultimately promoting a catabolic state." (PMID 38474705, 2024). "Additionally, diabetic patients treated with insulin face strict dietary restrictions, including limited carbohydrate intake, which can result in inadequate nutrient intake and potential malnutrition." (PMID 39364802, 2024). "Nutritional levels that may influence IGF-I secretion through insulin levels, fasting, malnutrition and food restriction have decreased plasma INS, IGF-I secretion, and IGF-I mRNA." (PMID 39748870, 2024). "Therefore, GH and IGF-1 levels should be carefully evaluated taking into account the nutritional state, as low insulin levels present in malnutrition make the liver resistant to GH contributing to reduce even more circulating IGF-1 levels." (PMID 37191429, 2023). "Even if the effect on fetal growth is minimal, malnutrition in utero may result in long-term alterations in insulin-glucose metabolism." (PMID 36359869, 2022). "Similarly, proxy to famine exposure, survivors of severe childhood malnutrition were also found to have reduced insulin sensitivity, or glucose intolerance." (PMID 35418574, 2022). "This could be partially explained by malnutrition and inflammation, two important players in the reverse epidemiology of this population, and they both counteract insulin sensitivity." (PMID 35889789, 2022). "IGF-1 deficiency in cirrhotic patients may be related to hepatocellular dysfunction, malnutrition, oxidative damage, altered lipid metabolism, and insulin resistance." (PMID 36374927, 2022). "Evidence that the cellular caloric restriction due to reduction in systemic insulin could hinder cell proliferation connects the two major effects of malnutrition, decreased blood glucose levels and stunting, both of which were observed in our pig model." (PMID 36118759, 2022). "In univariable analyses, prior malnutrition in adults, especially for those with BMI <17.0 indicating severe malnutrition, was associated with lower plasma insulin and insulin indices during an OGTT compared with people not previously malnourished." (PMID 33740034, 2021). "Potassium is the major intracellular cation and is taken up into cells as the cells increase in volume and number with the change to anabolism upon refeeding and as a direct result of insulin secretion, even though potassium had been depleted as a result of malnutrition in these individuals." (PMID 34362446, 2021).
malnutrition (continued). "Current nutritional recommendations for surgery primarily focus on screening and prevention of malnutrition, pre-surgical fasting protocols, and combating post-surgical insulin resistance, while recommendations regarding macronutrient composition and timing around surgery are less established." (PMID 34063333, 2021). "There is other evidence that changes of blood glucose levels during malnutrition occur due to an increased glucose production from other pathways, reducing insulin synthesis, stimulating the production of glucagon, and increasing circulating epinephrine levels." (PMID 32455002, 2020). "CR without malnutrition reduces the incidence of age‐associated disease and extends lifespan through mechanisms that include improvement of insulin sensitivity and cardiometabolic benefits, accompanied by enhanced cognitive and motor function." (PMID 29706024, 2018). "Through investigation of insulin, pituitary hormones, and thyroid hormones, we present evidence that nutritional deficiency due to reduced energy intake rather than primary pancreatic, pituitary, or thyroid dysfunction causes the small size in Trls2-/- mice." (PMID 29466436, 2018). "It was hypothesized that an epigenetic difference in beta cell dysfunction programmed from malnutrition can lead to a decrease in insulin sensitivity and altered whole‐body glucose metabolism in adulthood." (PMID 27664190, 2016). "Moreover, malnutrition alters the blood concentration of various hormones (e.g., insulin, thyroid hormones, glucocorticoids, and growth hormones)." (PMID 27833764, 2016). "Previous studies have shown that malnutrition is associated with a higher mortality rate in severe TBI patients, and early effective nutritional support may improve insulin resistance and patient prognosis." (PMID 27626493, 2016). "As this model differs from ours by its continuous postpartal malnutrition until day 21, such regimen might exert its influence on mammary gland development rather via changes in the actions of insulin and IGF-1, than via alteration of ovarian steroid levels." (PMID 24955840, 2014). "Moreover, González-Barranco and co-workers showed that malnutrition during the first year of life had an adverse effect on insulin responses after an OGTT." (PMID 21904606, 2011). "Additionally, malnutrition may trigger oxidative stress, impaired insulin signaling, lipid peroxidation, immune dysregulation, and accelerated aging, all of which amplify tissue damage and accelerate cerebral injury progression." (PMID 40777171, 2025). "In addition to sex hormones, insulin may also play an important role in the relationship between malnutrition and AD." (PMID 38515521, 2024). "Furthermore, emerging evidence has suggested that malnutrition could precipitate the onset of various pathologies, such as free radical damage, impaired insulin secretion, lipolysis, and lipid oxidation." (PMID 37645626, 2023). "Insulin is a signal that links metabolism with reproduction, particularly since Kiss1 neurons are sensitive to circulating metabolic signals such as leptin and insulin, which confirms their importance in mediating the body’s response to nutrition or malnutrition." (PMID 36297033, 2022). "Multiple factors may contribute to this condition, including malnutrition, protein-energy wasting, prolongation of insulin half-life due to decreased clearance, reduction of renal gluconeogenesis, accumulation of uremic toxin, and glucose removal by hemodialysis." (PMID 34496858, 2021). "However, chronic undernutrition is associated with low insulin production, and men who experienced severe malnutrition may develop persistent low insulin production even if their weight returns to normal." (PMID 33740034, 2021).
malnutrition (continued). "Conversely, Jamaican adult SAM survivors and controls were reported to have similar insulin sensitivity, insulin clearance, and adiponectin levels, but survivors of severe wasting had decreased glucose tolerance and worse pancreatic β cell function than survivors of edematous malnutrition." (PMID 33201860, 2020). "Furthermore, a case-control study fromJamaica showed that beta cell impairment and insulin sensitivity in adults with ahistory of under-nutrition varied by type of malnutrition and was worse in adultswith a history of marasmus than those with a history of kwashiorkor." (PMID 31673335, 2019). "This might be due to altered insulin sensitivity created during the time of malnutrition." (PMID 20700406, 2010). "Concomitant malnutrition in T2DM patients has been reported to elevate levels of HbA1c, RBG, insulin, and glucagon." (PMID 40977986, 2025). "It has been shown that in cases of malnutrition, both IGF-1 levels and GHR expression decrease; in addition, insulin and leptin synthesis are reduced in cases of inadequate nutrition." (PMID 39599588, 2024). "A previous study in a sheep model of malnutrition has also demonstrated a greater preponderance of very small adipocytes (<1,250 μm2 equivalent to <40 μm) in the SUB of LOW sheep with reduced insulin sensitivity." (PMID 37458462, 2023). "Furthermore, caloric restriction (CR) of 30% without an incurrence of malnutrition was associated with decreased adiposity and inflammation, and improved insulin sensitivity, blood glucose, inflammation and angiogenesis in non-obese humans, suggesting a feasible intervention for reducing CRF." (PMID 35406105, 2022). "Insulin concentration, fasting and during an OGTT, was normalized in women more than in men several years after adult malnutrition." (PMID 33740034, 2021). "In contrast, activation of IIS (via knockdown of the insulin pathway inhibitor PTEN) in intestinal stem and progenitor cells decreased fly resistance to malnutrition, potentially by affecting adipokinetic hormone signaling." (PMID 32225024, 2020). "We found that serum albumin, insulin and ferritin measures did not change as a result of the restricted diet, indicating that malnutrition was not induced." (PMID 27213441, 2016). "In conclusion, prior malnutrition alone is not a major driver of impaired insulin production but may contribute to it, especially in men." (PMID 33740034, 2021). "However, reduced protein translation is thought to facilitate Dietary Restriction (DR, defined as reduction in food intake without malnutrition) mediated lifespan extension, but not Insulin/IGF-1-dependent longevity." (PMID 23820781, 2013). "In rodents caloric restriction without malnutrition suppressed circulating IGF-1 and insulin levels in proportion to the level of restriction, increased insulin sensitivity and resistance to stress and toxicity, and reduced the cancer risk." (PMID 30774624, 2019).